MIR550A1 (microRNA 550a-1)
Synonyms: hsa-mir-550-1; MIR550-1; MIRN550-1; hsa-mir-550a-1; mir-550a-1
Gene: MicroRNA gene on chromosome 7 (30,289,794 to 30,289,890, forward strand). Ensembl gene ENSG00000207771.
Gene Ontology:
Biological process: miRNA-mediated post-transcriptional gene silencing
Cellular component: RISC complex